RNU6-684P (RNA, U6 small nuclear 684, pseudogene)
Gene: Small nuclear RNA gene on chromosome 14 (104,400,943 to 104,401,048, reverse strand). Ensembl gene ENSG00000222761.
Homologues: Orthologues: chimpanzee U6 (96% identical), macaque U6 (95% identical), dog U6 (58% identical), mouse Gm55765 (47% identical). Paralogues in human: RNU6-188P (81% identical), RNU6-838P (81% identical), RNU6-1152P (80% identical), RNU6-1260P (80% identical), RNU6-1024P (79% identical), RNU6-211P (79% identical), RNU6-317P (79% identical), RNU6-543P (79% identical), RNU6-686P (79% identical), RNU6-804P (79% identical), RNU6-98P (79% identical), RNU6-1060P (78% identical), and 1289 more.